RNU6-25P (RNA, U6 small nuclear 25, pseudogene)
Synonyms: RNU6-25
Gene: Small nuclear RNA gene on chromosome 3 (195,214,787 to 195,214,893, forward strand). Ensembl gene ENSG00000206600.
Homologues: Orthologues: pig U6 (97% identical), mouse Gm23932 (91% identical). Paralogues in human: RNU6-1 (99% identical), RNU6-2 (99% identical), RNU6-3P (99% identical), RNU6-4P (99% identical), RNU6-5P (99% identical), RNU6-6P (99% identical), RNU6-9 (99% identical), RNU6-12P (98% identical), RNU6-13P (98% identical), RNU6-17P (98% identical), RNU6-18P (98% identical), RNU6-29P (98% identical), and 1289 more.